AGTR1 (angiotensin II receptor type 1)
Diseases named in the same sentence as AGTR1 in open-access papers (continued):
Sharing a sentence is not in itself a finding about the gene and the disease.
Hypertension (continued). "Previous studies have found potential interactions between ACE, AGT, angiotensin II type 1 receptor (AGTR1), and α adducin (ADD1) variants and correlations between them and clinical endpoints in individuals with hypertension." (PMID 37091860, 2023). "It binds to the Ang II receptor type 1 (AGTR1) and works as a powerful vasoconstrictor, modulates aldosterone production, and remodels the heart and arteries, ultimately leading to hypertension and cardiac dysfunction." (PMID 37414816, 2023). "To date, more than 150 candidate genes for hypertension have been identified, and the human AT1 receptor gene (AGTR1) is one of them." (PMID 36577936, 2022). "AT1R is a G-protein-coupled receptor encoded by AGTR1 that binds to angiotensin II, leading to hypertension, vasoconstriction and vascular smooth muscle migration and proliferation." (PMID 35392097, 2022). "On the other hand, the AGTR1 and CYP11B2 genes are linked to the ACE inhibitor pathway and are used to treat cardiovascular disorders such as hypertension." (PMID 35629146, 2022). "The molecular docking results indicated that the active ingredients of GJD, puerarin, have significant binding activity with the primary hypertension targets AGTR1." (PMID 36046450, 2022). "Fimasartan is a drug used to treat hypertension that selectively blocks angiotensin II receptor type 1 and its safety and efficacy have been proven in various studies." (PMID 36451242, 2022). "Eleven of 20 approved drugs target AGTR1, and 10 out of the 11 drugs were Angiotensin II Receptor Blockers (ARBs), one of the most commonly used first-line treatments for hypertension, indicating its potential value in the treatment of IS." (PMID 35419038, 2022). "AT1 receptor gene (AGTR1) is related to essential hypertension (EH), and left ventricular hypertrophy (LVH) and arterial stiffness are common complications of EH." (PMID 36577936, 2022). "To examine the genotype distributions of CYP2C9 and AGTR1 among different grades of hypertension, we divided all hypertensive patients into three different grades based on the blood pressure levels." (PMID 33541272, 2021). "For COVID-19 patients with existing hypertension, the key targets and drugs are losartan, saralasin, telmisartan for targets AGTR1, AGTR2, and captopril for ACE and REN." (PMID 34067609, 2021). "In summary, FG-4592 treatment remarkably ameliorated hypertension and organ injury, possibly through stabilizing HIF1α and subsequently targeting eNOS, AGTR1, AGTR2, and oxidative stress." (PMID 34403364, 2021). "Noteworthy, literature data suggest that AGTR1 (Angiotensin II Receptor Type 1) can modulate hypertension, via the regulation of miR-26b-5p in arachidonic acid metabolism." (PMID 33233425, 2020). "Autoantibodies against angiotensin II receptor type 1 (AT1) have been discussed in relation to their role in hypertension for a long time." (PMID 31321561, 2019). "We further analyzed the association between AGTR1 A1166C and ESRD after adjusting age, sex, BMI, hypertension, DM, and smoking, because these factors differed between controls and cases." (PMID 29581855, 2018). "An increased risk of hypertension has been associated with angiotensinogen (AGT), angiotensin-converting enzyme (ACE), and angiotensin II receptor 1 (AGTR1)." (PMID 28903744, 2017). "Literature search from PubMed, Embase, and Cochrane databases were conducted using keywords “hypertension” or “pre-eclampsia,” “angiotensin II receptor type 1 autoantibody,” and its aliases from April 1999 to December 2015." (PMID 27124051, 2016). "This is the first report to evaluate the simultaneous association of ACE, AGTR1, and AGT gene polymorphisms in essential hypertension by haplotype based analyses and gender specific association in south India." (PMID 24860821, 2014).
Hypertension (continued). "A case-control association study was conducted to investigate a possible involvement of polymorphisms of three RAS genes: AGT M235T (rs699), ACE I/D (rs4340) and G2350A (rs4343), and AGTR1 A1166C (rs5186) in essential hypertensive patients." (PMID 24860821, 2014). "Of 41 SNPs genotyped, rs3789678 and rs2493132 within AGT, rs4305 within ACE, rs275645 within AGTR1, rs3802230 and rs10086846 within CYP11B2 were shown to associate with hypertension." (PMID 24015270, 2013). "According to the chi-square test P values (P<0.05) and odds ratios, rs3789678 and rs2493132 within AGT, rs4305 within ACE, rs275645 within AGTR1, rs3802230 and rs10086846 within CYP11B2 were shown to associate with hypertension." (PMID 24015270, 2013). "According to Chi-square test and logistic regression analysis, rs3789678 within AGT, rs4305 within ACE, rs275645 within AGTR1, rs3802230 within CYP11B2 were shown to associate with hypertension." (PMID 24015270, 2013). "While RAS is composed of a sophisticated interplay between multiple factors we propose a decrease of ACE2 to enforce AngII signaling via AGTR1 to ultimately result in vasoconstriction and hypertension." (PMID 21298017, 2011). "Here, we studied the effect of cyclosporine on HNF4α and various RAS components to better understand cyclosporine induced hypertension and proposed HNF4α dysfunction and subsequent regulation of AGTR1, ACE, and ACE2 as a molecular rational." (PMID 21298017, 2011). "ACE inhibitors and AGTR1-blocking drugs are already extensively exploited as therapy for hypertension." (PMID 20886000, 2010). "Hypothetically, if a loss-of-function miRSNP occurred in the AGTR1, ACE, AGT, REN, or ATP6AP2 gene, an increased incidence of hypertension, cardiac/vascular remodeling, and atherosclerosis would be observed." (PMID 20948563, 2010). "Our results indicate that clinical factors, such as a higher body mass index, elevated triglycerides, suboptimal glycemic control, and female gender, are more predictive of hypertension development than genetic risk factors like ACE and AGTR1 gene polymorphisms." (PMID 40149592, 2025). "A single genetic polymorphism of a gene such as ACE or AGTR1 may contribute to the risk of cardiovascular disease (CVD) and hypertension, either alone or in conjunction with other genetic factors." (PMID 40149592, 2025). "A high‐fat diet is known to accelerate the development of hypertension in animals, which is involved in increasing mitochondrial ROS levels, aggravating oxidative stress and enhancing angiotensin II receptor type 1 and angiotensin II levels in the kidneys and bloodstream." (PMID 40045164, 2025). "The relationship between AGTR1 and hypertension combined with renal injury was shown before." (PMID 40149592, 2025). "Furthermore, AGTR1 rs5186 and AGT rs699 were identified as risk factors for the development of hypertension in both ethnic groups." (PMID 38541065, 2024). "Studies suggest that AGTR1 in the kidney is responsible for hypertension in mammals." (PMID 37445727, 2023). "In this context, the overexpression of SIRT1 has been reported to attenuate angiotensin II-induced vascular remodelling and hypertension, which might be caused by SIRT1-induced downregulation of the angiotensin II type 1 receptor (AGTR1)." (PMID 37175937, 2023). "In addition, AGTR1 and NT5C2 were associated with pre-hypertension (FDR = 3.53E−02), and AGTR1 and KCNC4 were associated with adverse events associated with cardiac arrhythmia (FDR = 3.59E−02)." (PMID 37210443, 2023). "In contrast, MTHFR C677T, AGT T174M, and AGTR1 A1166C did not represent a higher risk for hypertensive disease." (PMID 36845669, 2023). "We found that the 2K1C-hypertension significantly increased Ang II and AGTR1 in the hippocampus, and the treadmill exercise could counteract the 2K1C-hypertensive effect." (PMID 35628344, 2022).
Hypertension (continued). "Of significant clinical interest, losartan is an FDA-approved AGTR1 antagonist for the treatment of hypertension, left ventricular hypertrophy, and diabetic nephropathy, and it has been clinically used for more than two decades with an excellent safety profile." (PMID 35739508, 2022). "In conclusion, PAN treatment induced upregulated renin secretion, which subsequently increased ANGII and AGTR1 expression and which may lead to the emergence of pathological conditions such as high blood pressure under certain circumstances." (PMID 35203286, 2022). "In addition, the frequency of AA genotype was 90.41% and that of CC genotype of AGTR1 was 0.29% in Han Chinese hypertension patients." (PMID 33541272, 2021). "In an angiotensin II (Ang II) hypertension model, FG-4592 abolished hypertensive responses; prevented vascular thickening, cardiac hypertrophy, and kidney injury; downregulated AGTR1 expression; and enhanced AGTR2, endothelial NO synthase (eNOS), and HIF1α protein levels in the aortas of mice." (PMID 34403364, 2021). "Variants of the AT1 receptor of angiotensin II (AGTR1) and other genetic polymorphisms such as the G protein-coupled receptor kinase 4 (GRK4) and solute carrier family 12 member 3, SLC12A3, have been related to arterial hypertension and atherosclerosis." (PMID 32714484, 2020). "Sartans, antagonists of AGTR1, are the cornerstone of medication for hypertension." (PMID 31772688, 2019). "Studies of hypertension have revealed that Ang II activates angiotensin II receptor type 1 (AT1R)." (PMID 31360120, 2019). "The aim of the present cross-sectional study was to investigate if polymorphisms of the RAS genes AGT, AGTR1, and ACE might be associated with an increased risk for higher blood pressure and hypertension in the Lithuanian children population." (PMID 28903744, 2017). "We also included known hypertension-related genes, including AGTR1, NOS3, and CSF1." (PMID 27779208, 2016). "The AGT and AGTR1 genes may be involved in common elements of the pathogenesis of hypertension, PE, and GH." (PMID 27910864, 2016). "AGTR1 is a G-protein-coupled receptor that mediates the major cardiovascular effects of angiotensin II, a potent vasopressor hormone involved in the development of hypertension, atherosclerosis, and insulin resistance." (PMID 23437094, 2013). "Valsartan is more specific in inhibiting angiotensin II receptor type 1 than telmisartan and exhibits different pharmacological effects, For example, telmisartan promotes insulin secretion in rat islets, whereas valsartan does not, and has a better therapeutic effect in hypertension than valsartan." (PMID 38288441, 2024). "A previous study summarized the pharmacogenomics of hypertension treatment, and the most common genetic variants involved in the metabolism of the five classes of drugs included ADRB1 (1165G > C), CYP2D6∗10, CYP2C9∗3, AGTR1 (1166A > C), ACE (I/D), CYP3A5∗3, and NPPA (2238T > C)." (PMID 38298191, 2024). "The estimated effect implied that AGTR1 may have a protective effect for hypertension." (PMID 28381821, 2017). "For example, AGTR1 blockers (ARBs) which are already in clinical use for treating hypertension, merit further investigation as a therapeutic strategy for AGTR1-positive cancer patients and may have the potential to prevent Ang II-AGTR1 signalling mediated cancer pathogenesis and metastases." (PMID 25981295, 2015). "In addition to GRK4, gene polymorphisms related to the renin-angiotensin-aldosterone system (RAAS), such as angiotensin converting enzyme (ACE), angiotensinogen (AGT), angiotensin II type 1 receptor (AGTR1), and aldosterone synthase (CYP11B2), have been reported to be associated with hypertension." (PMID 22518293, 2012). "In addition to calcineurin inhibition, cyclosporine stimulates PDGF and TGFβ signaling that seems to be involved in mediating renin secretory effects of cyclosporine and it is well established that binding of AngII to AGTR1 leads to vasoconstriction and hypertension." (PMID 21298017, 2011).
Hypertension (continued). "This review explores these dual challenges by examining the pharmacogenetic landscape of hypertension, with a focus on three clinically relevant genes: ACE, AGTR1, and CYP2C9." (PMID 41723221, 2026). "We found that AGTR1 A1166C (p = 0.01), AGT M235T (p = 0.01), AGT T174M (p = 0.02), hypertension (p = 0.03), smoking (p = 0.02), and family history of atherothrombotic disease (p = 0.04) were independently associated." (PMID 38025202, 2023). "Besides, it was reported that LVMI might be greater in the presence of ACE- DD and AGTR1-AC/CC polymorphisms in endurance athletes, which indicates that AGTR-1 polymorphisms promote LVH not only in patients with hypertension but also in healthy individuals with elevated LVMI." (PMID 36577936, 2022). "Angiotensin peptides bind to Agtr1 and Agtr2 receptors on vascular cells to help regulate vasoconstriction, and on the adrenal to stimulate secretion of aldosterone, leading to salt and water retention, which may be related to comorbidities of hypertension and obesity-related kidney damage." (PMID 33757938, 2021). "Combining the outcomes from both target lists, we selected ACE, AGT, AGTR1, and REN as important targets in COVID-19 for hypertension patients." (PMID 34067609, 2021). "Using 4,150 Thais recorded in the Electricity Generating Authority of Thailand (EGAT) study, we examined the association of rs1799752, rs699, rs5186, and rs1799998 located in or near ACE, AGT, AGTR1, and CYP11B2 genes in hypertension." (PMID 31511791, 2019). "This study aimed to investigate the association between 4 polymorphisms in RAAS genes (i.e., rs1799752 (ACE), rs699 (AGT), rs5186 (AGTR1), and rs1799998 (CYP11B2)) and hypertension in a Thai population." (PMID 31511791, 2019). "It is therefore unlikely that previous associations of some of the current candidates genes (VDR, FGB, AGTR1 and GPX1) with hypertension, have influenced our results, although this cannot be completely excluded." (PMID 22879966, 2012). "AGTR1 is a well-known regulator of blood pressure and common target of specific pharmacologic intervention (ARB) in hypertension." (PMID 20308035, 2010). "Notably, IRAP was markedly upregulated in hypertension and showed regulatory interactions with 14-3-3 proteins, modulating Nedd4-2, ACE2, and AGTR1 signaling." (PMID 40907688, 2025). "The ACE I/D and AGTR1 A/C gene polymorphisms, as part of the renin–angiotensin system (RAS), have been associated with the risk of hypertension, diabetes, CVD, and nondiabetic renal disease." (PMID 40149592, 2025). "In addition, the hypomethylation of TLR2, IFN-γ gene, ADD1, AGTR1, and GCK correlated with hypertension, the CES = 2.3%, 95% CI, −2.51–7.07." (PMID 31805646, 2019). "Thus, given the biological effects of these variants, it would be expected that the combination of risk genotypes, in this case DD of ACE, CC of rs699 and CC of AGTR-1, confer greater likelihood of developing MetS, DM2, hypertension and cardiovascular disease." (PMID 26910623, 2016). "Another study conducted in Chinese Han hypertensive patients also found that CYP2D6∗10 was not in HWE; this might be because CYP2D6∗10, AGTR1 (1166A > C), and NPPA (2238T > C) genes were associated with the development of hypertension." (PMID 38298191, 2024). "It has been observed that treatment with AGTR1 antagonists significantly reduces the total UPDRS score after one year in PD patients with hypertension, whereas this effect is not observed in patients receiving angiotensin-converting enzyme (ACE) inhibitor treatment." (PMID 38978048, 2024). "A latest animal experiment showed that Roxadustat can alleviate hypertension and organ damage through upregulation of angiotensin receptor type 2 (AGTR2) and endothelial NO synthase (eNOS), downregulation of angiotensin receptor type 1 (AGTR1), and inhibition of oxidative stress." (PMID 35318873, 2022).
Hypertension (continued). "The renin-angiotensin system (RAS) has been known to be related to heart health and angiotensin II type 1 (AGTR1) and type 2 receptor (AGTR2) in the RAS possess unique counterregulatory function in blood pressure regulation, which is crucial for the prevention of hypertension and CVD." (PMID 28792482, 2017). "For example, angiotensin II receptor type 1 (AGTR1), a potent vasopressor hormone and an important regulator of cardiovascular hemodynamics, appeared in two publications in 2008 and was not included in any PAH gene panel despite being directly related to PAH hypertension." (PMID 28768485, 2017). "This study aimed to detect hypertension and non-dipping phenomenon in adolescents with T1D in a population of Serbia and to determine its relationship with clinical data and genetic risk factors, including various variants of the ACE and AGTR1 gene polymorphisms." (PMID 40149592, 2025).
cardiac hypertrophy (141 papers, 2010 to 2025). "Downstream pathways mediated by the angiotensin II receptor type 1 are involved in myocardial hypertrophy." (PMID 37894940, 2023). "Increased cardiac Grk5 levels in Tg-RKIP mice are detrimental, because Grk5 contributes to pathological cardiac hypertrophy and Agtr1-stimulated fibrosis." (PMID 35203304, 2022). "Angiotensin II receptor type 1 (AT1) stimulation induces myocardial hypertrophy and fibrosis participating to HF worsening." (PMID 34299270, 2021). "Ang II plays a crucial role in regulation of cardiac hypertrophy via activation of angiotensin II receptor type 1 (AT1R) and type 2 (AT2R)." (PMID 33052248, 2020). "MiR-155 alleviates cardiac hypertrophy and improves heart function by repressing the expression of angiotensin II receptor type 1 (AGTR1) and suppression of its downstream calcium signaling pathways." (PMID 29094041, 2017). "The large increase of AGTR1 expression in Ross broilers under heat stress is an indicator of this change, because overexpression of AGTR1 in cardiomyocytes has been reported to induce cardiac hypertrophy and remodeling." (PMID 28407751, 2017). "However, the rs5186 C allele interrupts complementarity between miR-155 and the regulatory target site of AGTR1, thereby increasing AGTR1 levels, which may explain an increased degree of cardiac hypertrophy, oxidative stress, and fibrosis in FRDA patients." (PMID 28701783, 2017). "By sensitisation of the heart failure-promoting Gq/11-coupled AGTR1, RKIP enhances myocardial fibrosis and cardiac hypertrophy." (PMID 35203304, 2022). "The angiotensin II type 1 receptor (AGTR1) is a novel component of the renin-angiotensin system, and has a direct effect on blood pressure and heart hypertrophy." (PMID 24321324, 2013). "It has also been shown that CFEVs can target angiotensin II receptor type 1 (AT1R) and 2 (AT2R) and chronic activation of the myocardial renin-angiotensin system (RAS), leading to increased levels of angiotensin II (Ang II), which also contributes to cardiac hypertrophy and heart failure." (PMID 38543275, 2024).